TNF (tumor necrosis factor)
Diseases named in the same sentence as TNF in open-access papers (continued):
Sharing a sentence is not in itself a finding about the gene and the disease.
COVID-19 (continued). "Recently, several studies revealed that COVID-19 patients were mostly in a high systemic inflammatory status with severe cytokine storms (e.g., high levels of interleukin [IL]-6, IL-8, and tumor necrosis factor-α [TNF-α]), which contributed to fatal complications." (PMID 32733921, 2020). "Although the initiation of an anti-TNF agent in a patient with a mild case of COVID-19 seems safe and potentially beneficial, it remains important to note that more cases are required to properly assess which patients might benefit from its use as a therapeutic agent for COVID-19." (PMID 33426360, 2020). "Thus, TNF signaling is an early and persistent aspect of the COVID-19 disease progression." (PMID 33250777, 2020). "Increased level of HMGB1 can induce proinflammatory cytokine (TNF, IL-1, and IL-6) release, and since chronic inflammatory diseases result in HMGB1 increase, the severity in COVID-19 patients with underlying inflammatory comorbidities could be correlated to HMGB1 levels." (PMID 32948238, 2020). "Regulation of TNF-α expression may help reduce CRS in patients with COVID-19." (PMID 32987757, 2020). "In this study, IL-6, TNFα and IL-8 might be potential targets for immunotherapy of COVID-19." (PMID 33349241, 2020). "Indeed, in COVID-19, very critical patients display a cytokine storm syndrome with an increased secretion of interleukin (IL)-6, IL-1β, IL-17, IL-8, tumor necrosis factor (TNF)-α, interferon (IFN)-γ and other pro-inflammatory mediators." (PMID 32708322, 2020). "In addition, the IL-6:IL-10 and TNF-α:IL-10 ratios were significantly lower in COVID-19 patients as compared to non-COVID-19 patients (p = 0.0042 and p = 0.0001, respectively), driven by lower IL-6 and TNF-α levels in COVID-19 patients with similar levels of IL-10 between groups." (PMID 33272291, 2020). "Moreover, based on the frequent occurrence of CRS, which includes TNF-α as one of the predominant proinflammatory cytokines, during severe courses of COVID-19, it was speculated that TNF-α blockers such as infliximab may be an effective treatment of CRS." (PMID 33207589, 2020). "Moreover, the treatment with anti-TNF antibodies reduces the severity of lung disease for both influenza and respiratory syncytial virus, indicating that it could be efficient on COVID-19 cases." (PMID 32849309, 2020). "The present data indicate that DPSC administration might be effective in patients with COVID-19-induced hyper-inflammation, due to the inhibition in the production of several cytokines by activated T lymphocytes, namely, IFNγ, TNFα, IL-2, IL-9, IL-10, IL-17A, IL-18, IL-21, and IL-27." (PMID 33634100, 2020). "Interestingly, the numbers of total T cells, CD4+ T and CD8+ T cells are negatively correlated to levels of TNF-α, IL-6, and IL-10, respectively, suggesting these cytokines may be involved in the decrease of T cells detected in COVID-19." (PMID 32425950, 2020). "In our study, we also found that, compared to mild cases, the serum levels of IL-10, TNF-α and IL-6 were significantly higher in the severe cases, indicating that severe cases are prone to form an inflammatory storm, leading to rapid deterioration of COVID-19 eventually." (PMID 33154753, 2020). "Finally, CQ inhibits the synthesis of a myriad of pro-inflammatory cytokines such as TNF-α, IL-1, and IL-6, which may have deleterious effects on COVID-19 prognosis." (PMID 32423024, 2020). "This analysis shows that several inflammatory and viral cytokines remain elevated beyond the acute phase and are associated with cognitive deficits, including IL-6, IL-13, IL-8, IL-1β, TNFα, and MCP1 in long-term post-COVID-19 patients." (PMID 41516418, 2026). "Their research proved that increased TNF alpha and IFN gamma levels resulted in cytokine shock in mice and mirrored cytokine storm syndrome in COVID-19 patients." (PMID 40358160, 2025).
COVID-19 (continued). "Multiple studies have confirmed a positive correlation between the severity of COVID-19 and the levels of C-reactive protein (CRP), IL-2, IL-6, IL-7, IL-8, and TNF-α cytokines." (PMID 40371107, 2025). "Some changes were seen solely in COVID-19, including MDC versus MIP-1α (p < 0.01); TNF-α versus IL-1-β (p < 0.06); MCP4 versus TARC (p < 0.0001)." (PMID 40723800, 2025). "A recent study observed significant overexpression of NEAT1 in the blood of COVID-19 patients and found that NEAT1 is significantly correlated with cytokines such as IL-6, CCL2, and TNF-α." (PMID 40285022, 2025). "Future studies are required to determine how IGFBP2 inhibits cytokines—TNF-α and IL6—and chemokine—CCR5, are critical for improving COVID-19 outcomes." (PMID 40121473, 2025). "Elevated levels of interleukins (ILs) IL-2, IL-7, and IL-10, as well as tumor necrosis factor (TNF), have been shown to be significantly increased in patients with severe COVID-19 cases." (PMID 41007829, 2025). "However, biologic treatment (anti-TNF therapy) was less common among patients with flares compared to those without (7.2% vs. 23.2%; p = 0.003), while also a lower percentage of patients with flares had been previously vaccinated for COVID-19 (81.1% vs. 99.1%; p < 0.001)." (PMID 40142435, 2025). "This inflammatory response correlates with the severity of COVID-19 and is characterized by an increase in interleukins (ILs), IFN-γ, TNF-α, and other cytokines." (PMID 40869297, 2025). "Additionally, elevated serum angiotensin converting enzyme 2 levels, associated with increased TNF-α production, have been observed in COVID-19 patients, suggesting that anti-TNF-α therapies used in SLE could provide benefit in treating COVID-19, as reported in some studies." (PMID 40643149, 2025). "Currently, treatments targeting TNF-α and IFN-γ are effective at reducing mortality in COVID-19-infected mice." (PMID 39917294, 2025). "A drastic cytokine storm, characterized by considerably increased IL-6, IL-8, IL-10, TNF-α, and IFN levels in COVID-19 patients, leads to systemic inflammatory immune responses." (PMID 40872762, 2025). "Preferential mechanisms of cytokine responses were observed in patients with severe versus moderate COVID-19 patients, with IFN-alpha-mediated responses being more prevalent in the former subset, while TNF-alpha plays a role in the latter." (PMID 40051620, 2025). "Interestingly, as observed in human COVID-19 patients with fatal disease (KO and 1A0) and those with severe disease (6A4) had overall, significantly increased systemic levels of G-CSF, IL-6, IL-10, TNF-α, IL-12 (p40), IL-17A, CCL5, and CCL11 compared to those with moderate disease (6A2 and 1A3)." (PMID 40242753, 2025). "At baseline, compared to HD and LTBI/COVID-19, COVID-19 had elevated levels of pro-inflammatory cytokines IFN-γ (p<0.01) and TNF (p<0.05)." (PMID 40458413, 2025). "The analysis of cytokine profiles in pediatric patients with COVID-19, MIS-C, and healthy children revealed notable differences in levels of IL-1β, IL-6, IL-8, IL-12, TNF-α, and IFN-α levels." (PMID 40066463, 2025). "The incidence of HT among COVID-19 patients has sparked renewed interest among researchers, as these patients produce an excess of inflammatory cytokines (IL-6, IL-1β, IFN-γ, TNF-α)." (PMID 40584613, 2025). "A study that administrated 10 g of glutamine thrice daily found decreased IL-1β, TNF-α, and hs-CRP in COVID-19 outpatients." (PMID 40002722, 2025). "At very high exposure level, COVID-19-positive individuals demonstrated a continuous increase in IFN-γ, IL-2, IL-6, and IL-17A, while TNF peaked early and IL-10 showed minimal expression." (PMID 40406109, 2025).
COVID-19 (continued). "Elevated levels of pro-inflammatory cytokines, particularly interleukin-6 (IL-6), interleukin-17 (IL-17), and tumor necrosis factor-alpha (TNF-α), are hallmarks of both CRC progression and COVID-19 severity." (PMID 41048966, 2025). "The resulting network revealed several highly connected hub proteins, including IL1B, IL6, TNF, ACE, and REN, which are central regulators of inflammatory and cardiovascular pathways known to play key roles in COVID-19 pathogenesis." (PMID 41471341, 2025). "Activation of CD8+ and CD4+ T-cells, as well as the generation of TNF-α, IFN-γ, and IL-2, appears to be a significant effect of COVID-19 vaccinations." (PMID 39931582, 2025). "In the case of COVID-19, SARS-CoV-2 infection triggers a cascade of molecular disturbances, including excessive cytokine release (IL-6, TNF-α, and IL-1β), microglial activation, and oxidative stress, leading to neuroinflammation and neuronal dysfunction." (PMID 40126810, 2025). "Breastfeeding mothers with symptomatic or asymptomatic COVID-19 presented higher levels of several cytokines, such as IFN-γ, IL-4, IL-6, and TNF-α, compared to control groups." (PMID 40141241, 2025). "COVID-19 is known to impair all phases of wound healing through downregulation of ACE2, sustained cytokine activity (IL-6, TNF-α, IFN-γ), oxidative stress, and depletion of epidermal stem cells." (PMID 41446486, 2025). "Vaccination with various COVID-19 vaccines has been demonstrated to elicit spike protein-specific CD4+ and CD8+ T cell responses, which secrete interferon-gamma (IFN-γ) and tumor necrosis factor-alpha (TNF-α)." (PMID 41029649, 2025). "The aim of this work was to evaluate the associations of polymorphisms in the TNF-α, IL-6, IL-8, IL-10, CCL5 and CXCL6 genes with COVID-19 outcomes and with the serum levels of IFN-α, IFN-γ, TNF-α, IL-1Ra, IL-6, IL-7, IL-10, CCL2, CCL3, CXCL8, CXCL10 and GCSF." (PMID 40881695, 2025). "Concerning systemic immunity in COVID-19, clinical studies have shown a significant rise in pro-inflammatory cytokines and chemokines (IL-1β, IL-2, IL-6, IL-8, IL-15, IFN-γ, TNF, MCP-1), characterizing cytokine release syndrome (CRS) or cytokine storm." (PMID 40572294, 2025). "We and others demonstrated that several cytokines and chemokines including IL‐2, IL‐6, IL‐7, IL‐10, IL-15, IL-17, IP‐10, MCP‐1, TNF‐α, GCSF were related to disease severity and mortality in COVID-19." (PMID 40315230, 2025). "Recent studies show COVID-19 convalescents had a higher level of CETP than the healthy cohort and lipoprotein lipase was impaired by the elevated IL-6 and TNF-α in addition to increased hepatic lipase in the LC cohort." (PMID 40335840, 2025). "In patients with the PAP phase of COVID-19, an increase in proinflammatory cytokines, namely, IFN-α, TNF-α, G-CSF, IL17A, IL-6, IL1-β, and IL-13, has been confirmed in a number of studies." (PMID 40002929, 2025). "Therefore, blocking of TNF might inhibit COVID-19 related organ damage." (PMID 38510457, 2024). "COVID-19 patients also revealed a major increase in C-reactive protein (CRP), IL-2, IL-4, IL-6, IL-10, TNF-α, and IFN-γ." (PMID 38540252, 2024). "Cytokine profiling of the sera of patients with COVID-19 and the transcriptional analysis of their BAL fluid revealed increased IL-6, G-CSF, CXCL10, CCL2, CCL3, and TNF-α levels, correlating with disease severity and progression." (PMID 39417078, 2024). "EGCG also can block the activation of NF-κB to controls the expression of many pro-inflammatory cytokines, including IL-1β, TNF-α, IL8, IL-6, all of which are induced in COVID-19." (PMID 38632501, 2024). "Overall, our study clarified the interplay between IL-2, TNF-α, IFN-γ, and CRS in patients with COVID-19 and highlighted potential avenues for therapeutic intervention." (PMID 39359733, 2024).
COVID-19 (continued). "Despite these differences, prior research has consistently shown elevated inflammatory cytokines, such as IFN-γ, IL-10, IL-6, IL-8, CXCL10, MIP-1α, MIP-1β, TNF-α, and IL-17 in MIS-C patients compared to healthy controls and other pediatric COVID-19 cases." (PMID 39931580, 2024). "In fact, when compared to controls, amniotic fluid from COVID-19-affected pregnancies demonstrated elevated levels of several pro-inflammatory cytokines, including IL-12 p40, CCL4, CCL7, CCL13, TNF, IL-1a, IL-17A, and IL-17E." (PMID 39390219, 2024). "The production of TNF-α is central to acute inflammatory processes and it is enhanced in ARDS patients, individuals with severe COVID-19, and individuals with other forms of severe pneumonia." (PMID 38887291, 2024). "NAR can not only reduce the lung injury induced by COVID-19 by inhibiting interleukin-6 (IL-6), but also block LPS-induced pulmonary edema by inhibiting the secretion of MPO, tumor necrosis factor-α (TNF-α) and neutrophil infiltration." (PMID 38755662, 2024). "The CSF2, IFNG, and IL1B expression levels were considerably lower in the COVID-19 than in the Healthy group, while those of IL6R, TLR2, TLR4, and TNF were higher." (PMID 38165854, 2024). "Another study of TB/COVID-19 co-infection showed higher plasma concentrations of TNF-α, MIP-1β, and IL-9 compared to COVID-19 patients, and higher concentrations of IL-1β, TNF-α, IL-17A, IL-5, FGF-basic, and GM-CSF compared to TB patients." (PMID 38994357, 2024). "A cytokine storm is a severe immune response characterized by the overproduction of proinflammatory cytokines, such as TNF-α and IFN-γ, leading to tissue damage and mortality in COVID-19 patients." (PMID 38899916, 2024). "Moreover, a previous review study of thousands of COVID-19 patients in China about leukocyte changes and cytokine storm in mild versus severe cases confirmed that mild and severe conditions affected circulating leukocyte subsets and cytokine secretion, including TNF." (PMID 38187222, 2024). "Frequencies of TNF-α rs1800629 GA, AA, IL-8 rs4073 TA, AA, IL-10 (-1082 G>A), rs1800896 GA and GG, and CXCR2 rs2230054 CT genotypes were significantly higher in COVID-19 patients compared to the control group (p < 0.05)." (PMID 38544825, 2024). "Patients with severe COVID-19 with CRS often exhibit activation of NF-κB, as well as upregulation of TNF-α and IFN-γ." (PMID 39359733, 2024). "The diminished antibody response to the COVID-19 vaccines is attributed to the well-documented impact of the CTLA-4-Ig and TNF-α inhibitors on reducing the frequency of peripheral memory B cells in humans’ peripheral blood." (PMID 39456932, 2024). "In one study, it was noted that the activation of the innate immune system and cytokine storms (featuring elevated levels of TNF, IL-6, CXCL10, CCL2, CCL5, and IFN2) play crucial roles in the pathogenesis of COVID-19." (PMID 39685844, 2024). "Severe adult COVID-19 and MIS-C are characterized by excessive inflammation, including elevated inflammatory cytokines and chemokines such as tumor necrosis factor alpha (TNF-α), interleukin (IL) 6, IL-10, and IL-1β." (PMID 39494457, 2024). "In mild-moderate COVID-19, the cytokine storm is similar to that observed in typical ALI and ARDS, with increased levels of proinflammatory cytokines such as IL-1β, IL-6, and TNF-α." (PMID 39130641, 2024). "In contrast to the control group, the COVID-19 T2DM groups exhibited a significant increase in PAR-1, NT-proBNP, HbA1c, IL-6, D-dimer, TNF-α, CRP, and homocysteine." (PMID 38675414, 2024). "Thus, TNF-α could be considered a potential therapeutic target for severe COVID-19." (PMID 39652608, 2024). "Markers found to be significantly elevated in COVID-19 compared to control samples included CCL19, CXCL-13, MCP-3, PGF, HGF and TNF." (PMID 39767799, 2024).
COVID-19 (continued). "Cytokines are messenger molecules of the immune system, including IL-6, IFN-α, IL-1β, IL-8, IL-10, IFN-γ, TNF-a, and C-reactive protein (CRP), and as such, they are closely related to the worst outcomes of COVID-19." (PMID 38012459, 2024). "Furthermore, a Structure–Activity Relationship analysis revealed that furosemide’s sulfonamide groups may interact with cytokine sites such as tumor necrosis factor-alpha (TNF-α) and interleukin-6 (IL-6), potentially explaining its beneficial effects in COVID-19 management." (PMID 39065617, 2024). "PANoptosis, driven by TNF-α and IFN-γ, perpetuates cytokine storm and multi-organ injuries in COVID-19." (PMID 38555477, 2024). "Individuals who received dexamethasone had significantly lower levels of TNFα, IL6 and IL1β by 21–24 weeks in multivariable analyses, in contrast to findings at 9–12 weeks after COVID-19 onset." (PMID 39008486, 2024). "Endothelial activation has been reported to be triggered by several stimuli, including bacterial endotoxins and inflammatory cytokines such as TNF-α, ILs, and IFN-γ, and it has been identified as a common feature in both ME/CFS and post-COVID-19 condition." (PMID 38600563, 2024). "These molecules modulate CS in COVID-19, notably meloxicam, which exhibited a downregulatory effect on cytokines (IL-6, CCL2, GM-CSF, CXCL10, IL-2, and TNF-α)." (PMID 39518964, 2024). "Cytokines such as interleukin-1 (IL-1), IL-6, IL-12, and tumor necrosis factor α (TNFα), some of which may be produced through mechanisms involving nuclear factor kappa B (NF-κB), likely contribute to the hyperinflammatory state in patients with severe COVID-19." (PMID 40012912, 2024). "Severe COVID-19 cytokine release during SARS-CoV-2 infection is partially triggered by increased angiotensin II, possibly as a result of TNF-α overproduction." (PMID 38794167, 2024). "Pro-inflammatory cytokines such as interleukins IL-2, IL-6, tumor necrosis factor-alpha (TNF-α), interferon-gamma (IFN-γ), and many other molecules, including chemokines, play a significant role in the pathophysiology of COVID-19." (PMID 38707035, 2024). "Other inflammatory pathways showed a mixture of upregulation and downregulation in the Malawian cohort compared to HLCA cohorts, including IL6/JAK/STAT (green arrow) and TNF-NFKB (blue arrow)—key targets for therapies being used in COVID-19." (PMID 39567718, 2024). "The aim of this study was to analyze the potential relationship between the level of selected cytokines (IL-6, IL-10, IL-12, IL-15, TNF-α) and inflammatory markers (CRP, NLR, PLR, LMR, SII) and the duration of rehabilitation in patients after COVID-19." (PMID 39335569, 2024). "In acute COVID-19, cGAS, STING, IFN-α, TNF-α, and IL-6 levels were higher in patients with severe disease than in those with nonsevere manifestations (p < 0.05)." (PMID 38424312, 2024). "In particular, elevated levels of IL-6, IL-7, IL-10, IL-17, IL-23, TNFα, IFN-γ, IFNα or IL-1β have been found in severe COVID-19 cases and have already profoundly been analysed in recent Meta-Analysis." (PMID 38298642, 2024). "In particular, a study linking COVID-19 and CH showed an increased inflammatory response from monocytes in severe COVID-19 patients with CH, mediated via interferon gamma (IFN-γ) and TNF-α signaling signatures." (PMID 39641768, 2024). "In the analysis of plasma cytokine levels, it was observed that patients with the severe form of COVID-19 had higher levels of IFN-α (p = 0.0006), TNF-α (p = 0.0137) and IL-6 (p = 0.0071) than those with the nonsevere form." (PMID 38424312, 2024). "Individuals with symptomatic COVID-19 had higher levels of four cytokines (IL-6, IFN-γ, TNF-α, and IL17) than healthy controls." (PMID 38459174, 2024). "IL-6, TGF-beta, and TNF-alpha are all cytokines that have been found to have connections with GSH and COVID-19." (PMID 38539805, 2024).